APOE (apolipoprotein E)
Diseases named in the same sentence as APOE in open-access papers (continued):
Sharing a sentence is not in itself a finding about the gene and the disease.
coronary atherosclerosis (37 papers, 2009 to 2025). Atherosclerosis of the coronary vasculature. "The relationship between APOE gene polymorphisms and coronary atherosclerosis susceptibility in hypertensive population is unclear." (PMID 39261765, 2024). "Given the fact that cholesterol-fed rabbits are known to develop coronary atherosclerosis, we were motivated to investigate the effect of apoE deficiency on the coronary atherosclerosis." (PMID 39087075, 2024). "The rs429358 and rs7412 polymorphisms of APOE were genotyped, and relationship between APOE polymorphisms and the risk of coronary atherosclerosis in hypertensive patients were analyzed." (PMID 39261765, 2024). "This study is the first to report on APOE gene polymorphisms and coronary atherosclerosis susceptibility in hypertensive patients." (PMID 39261765, 2024). "The same study demonstrated that isolating anti-HSP60 antibodies from humans with coronary atherosclerosis and injecting them into apolipoprotein E-deficient mice caused significant increases in aortic atherosclerotic lesions." (PMID 23304456, 2012). "However, the relationship between APOE polymorphisms and coronary atherosclerosis susceptibility in hypertensive patients is unclear." (PMID 39261765, 2024). "In addition, some studies have found that APOE polymorphisms are also associated with the severity of coronary atherosclerosis." (PMID 39261765, 2024). "The discovery in 1993 of the association of the apoE-ε4 allele with AD revived interest in the vascular hypothesis as the ε4 allele was already known to be associated with coronary atherosclerosis." (PMID 21266042, 2011). "The frequency of APOE ɛ3/ɛ4 was higher (16.4% vs. 10.9%, p = 0.001) in the patients with coronary atherosclerosis than controls." (PMID 39261765, 2024). "The frequency of the APOE ɛ3/ɛ3 genotype was lower (69.7% vs. 74.3%, p = 0.036), and ɛ3/ɛ4 genotype was higher (16.4% vs. 10.9%, p = 0.001) in the patients with coronary atherosclerosis than those in controls." (PMID 39261765, 2024). "The mismatch between Aβ and apolipoprotein E (ApoE) promotes coronary atherosclerosis and then ischemic cardiac disease." (PMID 36910141, 2023). "One study using a PD containing 15% of fat successfully induced coronary atherosclerosis in an ApoE KO rat model." (PMID 34361033, 2021). "In contrast, restoration of SR-BI expression in bone marrow derived-cells reduced diet induced aortic and coronary artery atherosclerosis, myocardial fibrosis and the increase in heart weights in SR-BI-null; apoE-hypomorphic mice." (PMID 23967310, 2013). "The results of χ2 test showed that the APOE rs429358 and rs7412 in the patients with coronary atherosclerosis (χ2 = 0.797, p = 0.372; and χ2 = 0.0003, p = 0.986), and controls (χ2 = 2.094, p = 0.148; and χ2 = 0.448, p = 0.503) conformed to the Hardy-Weinberg equilibrium, respectively." (PMID 39261765, 2024). "Second, this study also did not take into account the effects of gender and puberty on phenotype because only male ApoE−/− pigs were investigated and development of coronary atherosclerosis was observed in the ApoE−/− pigs on HFHC feeding for 6 months, when they have reached puberty." (PMID 30305304, 2018). "Furthermore, knockdown of eNOS in ApoE-/- mice showed increased lesions area with peripheral coronary atherosclerosis with myocardial fibrosis compared with ApoE-/- alone." (PMID 20663150, 2010). "In addition, ApoE–/–:Ins2+/Akita male mice fed a Western diet (hyperglycemic and hyperlipidemic mice) also have coronary atherosclerosis, MI and a significant reduction in lifespan, while chronic intermittent mental stress promotes plaque instability and MI in ApoE(–/–)fibrillin-1 (C1039G±) mice." (PMID 36093131, 2022).
coronary atherosclerosis (continued). "In addition, increased ApoCIII levels in HDL may attenuate the anti-atherogenic effects of ApoE, thereby accelerating coronary atherosclerosis." (PMID 23173569, 2012).
lung cancer (37 papers, 2011 to 2025). A malignant neoplasm involving the lung. "Another study also showed that increased ApoE expression was clinically significantly correlated with malignant pleural effusion-associated lung cancer patient survival." (PMID 31275318, 2019). "Higher plasma ApoE concentrations (> 5.9 mg/dL) are the independent risk factor for hemorrhage during EBB in patients with lung cancer." (PMID 30031394, 2018). "The aim of this study was to explore the association of plasma ApoE with the risk of EBB-induced bleeding in patients with lung cancer." (PMID 30031394, 2018). "Nevertheless, recent data have implicated that long-term overexpression of APOE can promote cell proliferation and increased risk of lung cancer among patients." (PMID 29552057, 2017). "Mustard lungs were associated with increased expression of FOXM1 and APOE genes, which suggests an increased risk of lung cancer among these patients." (PMID 29552057, 2017). "We considered the expression of Forkhead box M1 (FOXM1) and apolipoprotein E (APOE) genes, which are responsible for cell proliferation, differentiation, tumorigenesis, and increased risk of lung cancer, in the lung bronchial tissue of patients exposed to SM." (PMID 29552057, 2017). "Similar studies have identified the APOE ε4 allele as a lung cancer risk factor." (PMID 39763652, 2024). "Furthermore, the APOE ε2/ε2 genotype displayed a higher risk of cancer development compared to APOE ε2/ε3, particularly in patients with advanced stages of lung cancer, suggesting a potential association with cancer progression stages." (PMID 39763652, 2024). "Furthermore, in lung cancer, APOE has been implicated in promoting cancer proliferation and migration, and its overexpression has been linked to a more aggressive features in patients with lung adenocarcinoma." (PMID 38054821, 2023). "All of these data suggest that high levels of ApoE are associated with lung cancer." (PMID 35892323, 2022). "We speculate that increased expression of FOXM1 and APOE genes is more likely linked to overproduction of ROS and OS in mustard lungs that may increase the risk of lung cancer among these patients." (PMID 29552057, 2017). "Therefore, overexpression of FOXM1 and APOE due to increased level of ROS and OS may induce the risk of lung cancer in these patients." (PMID 29552057, 2017). "Apolipoprotein APOA1 and APOE-carrying EVs are also increased from nonsmall cell lung cancer cell A549 treated with cisplatin, a platinum-based alkylating agent that binds to DNA and inhibits replication of cancer cells." (PMID 40089067, 2025). "A growing body of evidence implicates apolipoproteins (particularly ApoA-I and ApoE) as key modulators of lung cancer metastasis through both vascular and immune pathways." (PMID 40862704, 2025). "In conclusion, our investigation elucidates the pivotal role of OVOL1 in modulating the proliferation and metastasis of non‐small cell lung cancer (NSCLC) via its governance on APOE‐mediated cholesterol metabolic pathways." (PMID 40437660, 2025). "Previous reports have confirmed the tumourigenic and metastatic capabilities of APOE in pancreatic, breast, and lung cancers." (PMID 39138838, 2024). "It would have been beneficial to analyze the correlation between APOE levels and lung cancer staging if such data had been available." (PMID 39763652, 2024). "Previous reports have primarily focused on APOE protein expression levels in patients with lung cancer." (PMID 39763652, 2024). "In CRC and lung cancer we also observed high expression of APOE, encoding Apolipoprotein E, restricted to CD68+CD163+ macrophages." (PMID 36724681, 2023). "In contrast, C1QC+ TAMs expressed the classical TAM-associated genes C1QA, C1QB, C1QC, APOE, and TREM2, which were previously reported in lung cancer." (PMID 37383234, 2023).
lung cancer (continued). "ApoE is intensively related to squamous metaplasia of the lung, indicating that ApoE can be a predictive biomarker for the early stage of lung cancer, especially for current smokers." (PMID 36506554, 2022). "APOE is significantly highly expressed in lung cancer, and its overexpression promotes cancer proliferation and migration, and aggressiveness of lung cancer." (PMID 35090515, 2022). "Not only is ApoE a potential biomarker for lung cancer, but it has also been reported to be one of the biomarkers to help diagnose breast cancer in men." (PMID 35892323, 2022). "Clinical analyses showed that ApoE expression was increased in breast, ovarian, gastric, prostate and lung cancers." (PMID 31275318, 2019). "The levels of ApoE are significantly elevated in malignant pleural effusions of lung cancer patients." (PMID 31275318, 2019). "Oncomine analysis of okayama lung cancer database showed that expression of ApoE was upregulated in lung cancer patients." (PMID 31275318, 2019). "In human lung cancer, the levels of ApoE gene expression were significantly higher in cancer tissue than in adjacent non-cancer tissue." (PMID 31275318, 2019). "Knockdown of ApoE expression in lung cancer cells and B16F10 cells also decreased cancer cell growth and metastasis." (PMID 31275318, 2019). "ApoE has been found to be related to lung cancer and considered to be a useful marker for assessing NSCLC patients with lymph node metastasis." (PMID 31788012, 2019). "Expression of cell cycle regulatory proteins CDK4, CDK6, and cyclin D1 was significantly decreased in ApoE knockdown lung cancer cells." (PMID 31275318, 2019). "Inhibition of ApoE expression resulted in the inhibition of lung cancer cell (A549 and NCI-H460) proliferation in a time-dependent manner compared to cells transfected with negative control siRNA." (PMID 31275318, 2019). "By contrast, ApoE appears to facilitate neoplastic dissemination: elevated ApoE expression in lung cancer cells enhances adhesion to LRP1-expressing endothelium, promotes transendothelial migration under disturbed flow, and increases metastatic colonization in distal organs." (PMID 40862704, 2025). "APOE gene can influence the uptake and breakdown of TC and TG in lung cancer patients." (PMID 39763652, 2024). "Knockout of ApoE in mice can inhibit lung cancer cell proliferation and metastasis." (PMID 36506554, 2022). "Our study suggests the development of a broadly applied approach targeting a specific subset of TAMs in lung cancer may yield similar benefits given the engagement of a shared pro-tumorigenic transcriptional program across APOE-high myeloid cells in metastatic LNs." (PMID 40835684, 2025). "Moreover, a recent study has shown that activation of the axial mechanism of liver-X nuclear receptor (LXR) and ApoE by pharmacological agents can elicit an immune response against a variety of cancers, such as glioblastoma, ovarian, renal, colon cancers, and lung cancer." (PMID 35892323, 2022). "Also, APOE was observed to have decreased in lung cancer tissues." (PMID 34063271, 2021). "Additionally, we investigated the ApoE expression levels in normal and lung cancer patients." (PMID 31275318, 2019). "In order to reduce the risk of biopsy-induced bleeding, especially for massive bleeding during bronchoscopy, it may be appropriate to maintain the levels of plasma ApoE between 3.5 mg/dL and 5.9 mg/dL prior to aggressive biopsy on endobronchial exophytic lesions in lung cancer patients." (PMID 30031394, 2018). "In conclusion, our study showed that plasma ApoE is associated with the risk of EBB-induced bleeding in patients with lung cancer in a non-linear pattern, and the relative safe levels of ApoE may be 3.5–5.9 mg/dL." (PMID 30031394, 2018). "studies demonstrate APOE-mediated angiogenesis via VEGF upregulation in bladder cancer, while lung cancer research reveals its EMT-inducing capacity through ZEB1/vimentin axis activation." (PMID 41390817, 2025).
lung cancer (continued). "In lung cancer cells and B16F10 cells, APOE expression was knocked down, which reduced tumor development and metastasis." (PMID 36908705, 2023). "APOE knockout inhibits tumor growth and metastasis by increasing REEM-1-mediated infiltration of NK cells in lung cancer." (PMID 35090515, 2022). "ApoE knockout inhibits tumor growth and metastasis by increasing REEM-1-mediated infiltration of natural killer cells in lung cancer." (PMID 35892323, 2022). "In contrast, TAM-like macrophages expressed a set of genes (APOE, C1QA, C1QB and TREM2), which was found previously to be expressed in the TAMs of lung cancer." (PMID 36466840, 2022). "Recent studies have also indicated that apolipoprotein E (ApoE), which is involved in cholesterol metabolism, is overexpressed in human lung cancer tissues compared with adjacent non-cancerous tissues." (PMID 38983267, 2024). "In addition to the correlation between APOE upregulation and increased lung adenocarcinoma frequency, APOE is associated with a higher incidence of malignant pleural effusions (MPEs), a complication of lung adenocarcinoma, compared to lung cancers without MPEs." (PMID 38067270, 2023). "Additionally, our findings indicate that the absence of APOE prevented the proliferative capacity of the cells and mitigates the invasiveness and migratory propensity of non‐small cell lung cancer cells." (PMID 40437660, 2025). "Concerning the comparison between the normal group and the advanced-stage lung cancer group (stage-IIIb and IV), similarly 4 peptides (APOA4 268–284, APOA4 271–283, FIBA 5–15, and APOE 194–214) did not satisfy the criterion of p<0.05." (PMID 21533267, 2011).
prostate carcinoma (37 papers, 2009 to 2025). A carcinoma that arises from epithelial cells of the prostate gland. "The role of APOE in prostate cancer is multifaceted, with studies showing its close association with tumor progression and prognosis." (PMID 41343534, 2025). "They utilized these cell lines to explore the influence of genetic variants of APOE on prostate cancer." (PMID 36506554, 2022). "While these studies were generally focused on the transcriptional regulation of tumor aggressiveness by ApoE, the present study exclusively investigated the relationship between ApoE variants and acknowledged aggressive prostate cancer cell lines." (PMID 23934233, 2013). "In this study, we explored the association between ApoE phenotypes of prostate cancer cell lines and the risk of aggressive prostate cancer." (PMID 23934233, 2013). "Taken together, these exploratory findings support the premise that in prostate cancer cell lines, efficient cholesterol efflux and its resultant depletion is associated with certain ApoE isoforms." (PMID 23934233, 2013). "Further studies have explored the impact of APOE gene polymorphisms on prostate cancer." (PMID 41343534, 2025). "Immunohistochemical analysis revealed that APOE protein expression positively correlates with Gleason scores, suggesting that elevated APOE expression in prostate cancer cells may be associated with high invasiveness." (PMID 41343534, 2025). "Because APOE regulates cholesterol levels, variation in lipoprotein E may explain its association with the risk of prostate cancer." (PMID 34873574, 2021). "The polymorphism of APOE may play a significant role in prostate cancer." (PMID 36506554, 2022). "First, APOE expression in prostate cancer correlates with tumor aggressiveness and hormone independence." (PMID 41343534, 2025). "The APOE genotype also modulates the physiology in prostate cancer cells by modulating cholesterol metabolism." (PMID 41465180, 2025). "As a result, AR, TREM2, and APOE are overexpressed in prostate cancer and correlate with poor prognosis The role of SPP1-expressing TAMs in tumor progression is under active investigation, and high SPP1 expression is linked to an unfavorable prognosis." (PMID 41417432, 2025). "In prostate cancer, apolipoprotein E (APOE) in the TME binds to TREM2 on macrophages and promotes androgen receptor (AR) expression, which further upregulates the transcription of immune mediators such as IL-10, TGF-β1, IL-23A, and CCL2." (PMID 41417432, 2025). "They discovered that APOE secreted by prostate tumor cells induces the senescence of TREM2 + immunosuppressive neutrophils, which are associated with poor prognosis in prostate cancer patients." (PMID 41343534, 2025). "A recent paper suggested that APOE, secreted from prostate cancer cells, can bind to TREM2 on neutrophils and drive them towards a senescent phenotype that promotes tumor progression." (PMID 40523023, 2025). "In prostate cancer, tumor-derived apolipoprotein E (APOE) binds to triggering receptor expressed on myeloid cells 2 (TREM2) on neutrophils, activating DAP12/SYK signaling." (PMID 40805288, 2025). "Neutrophils and NK cells are the key components of the innate immune system, and prior studies have shown that prostate cancer cells induce senescence in TREM2+ immunosuppressive neutrophils by secreting APOE." (PMID 40242752, 2025). "In a mouse model of prostate cancer, tumor cell-released apolipoprotein E (APOE) interacts with triggering receptor expressed on myeloid cells 2 (TREM2) on neutrophils, triggering the senescence process in neutrophils." (PMID 38760815, 2024). "Based on previous research and preliminary analysis, we focus on the function of APOE gene in prostate cancer." (PMID 38349474, 2024). "A previous study has shown that prostate cancer cells promote the senescence of TREM2 + immunosuppressive neutrophils by secreting APOE, which exerts immunosuppressive and tumor-promoting effects." (PMID 37664173, 2023).